BDNF (brain derived neurotrophic factor)
Diseases named in the same sentence as BDNF in open-access papers (continued):
Sharing a sentence is not in itself a finding about the gene and the disease.
periodontitis (10 papers, 2014 to 2026). An acute or chronic inflammatory process that affects the tissues that surround and support the teeth. "This study addresses an under-researched area by investigatingthe roles of Vitamin D and Brain-Derived Neurotrophic Factor (BDNF) in periodontitis associated neuropsychiatric conditions." (PMID 40822814, 2025). "Chronicinflammation, commonly seen in periodontitis, can lead to alterations in BDNF expression disrupting the normal function." (PMID 40822814, 2025). "Patients with both periodontitis and neuropsychiatric disorders showed significantly higherage, BMI, plaque index and probing depth and lower Vitamin D, BDNF levels and mental health scores (p < 0.001)." (PMID 40822814, 2025). "The present study is the first to demonstrate that BDNF levels were increased in periodontal tissues from chronic periodontitis compared to healthy subjects." (PMID 25587209, 2014). "The aim of this study was to measure the levels of BDNF in periodontal tissues from patients with chronic periodontitis." (PMID 25587209, 2014). "The aim of this study was to analyze the BDNF levels in periodontal tissues of patients with chronic periodontitis (CP) and periodontally healthy controls (HC)." (PMID 25587209, 2014). "However, in our study, animals exposed only to periodontitis (P+CMS‐) exhibited modest effects on the BDNF pathway, suggesting that CMS is the dominant factor driving the observed changes in the combined group (P+CMS+)." (PMID 41326981, 2025). "The current study provides novel insights exploring the role of Vitamin D and Brain-Derived Neurotrophic Factor (BDNF) in patientswith periodontitis and neuropsychiatric disorders, highlighting the complex interplay between periodontal inflammation, metabolicdysregulation and mental health." (PMID 40822814, 2025). "From a neurobiological perspective, brain-derived neurotrophic factor (BDNF) has been shown to exhibit depressive-like behavior in animal models of periodontitis, indicating that neurobiological pathways may be involved in linking these conditions." (PMID 39700175, 2024). "Investigating the impact of periodontitis on Vitamin D and Brain-Derived Neurotrophic Factor(BDNF) expression in patients with neuropsychiatric disorders could yield valuable insights into how the oral and systemic inflammationinfluences the development and progression of neuropsychiatric disorders." (PMID 40822814, 2025). "However, a negative correlation between the production of BDNF and IL-10 was observed in samples from patients with periodontitis." (PMID 25587209, 2014).
transient cerebral ischemia (10 papers, 2014 to 2023). "Moreover, a previous study reported that brain-derived neurotrophic factor (BDNF) genetically modified mice had improved motor dysfunction following transient cerebral ischemia." (PMID 33920851, 2021).
Zinc deficiency (10 papers, 2013 to 2025). A deficiency of the essential metal Zinc; an essential cofactor for many enzymes. "Zinc in particular is required for proper BDNF signaling in the brain; experimental zinc deficiency leads to impaired BDNF signaling and cognitive dysfunction." (PMID 41142318, 2025). "In fact, the independent actions of Src and BDNF have been reported in the past as a response to a dietary imbalance caused by zinc deficiency." (PMID 24632812, 2014). "To further confirm that zinc deficiency is involved in hippocampal BDNF deficit, we injected zinc sulfate into the rat brains, with or without intraperitoneal injection of zinc chelator CQ." (PMID 23383172, 2013). "Taking together, zinc overdose results in hippocampal synaptic zinc deficiency, which further reduce BDNF-TrkB neurotrophic signaling, the latter, promoted the memory impairment." (PMID 23383172, 2013). "High dose supplementation of zinc induces specific zinc deficiency in hippocampus, which further impair learning and memory due to decreased availability of synaptic zinc and BDNF deficit." (PMID 23383172, 2013). "Other added values of this approach are based on the fact that zinc supplementation is a powerful driver for neurotrophic signaling and neuronal plasticity that is mediated by increased levels of the Brain-derived neurotrophic factor (BDNF) and that AD patients suffer from slight zinc deficiency." (PMID 32784855, 2020). "Furthermore, the decreased expression of NMDA receptors and scaffolding proteins both in dietary zinc deficiency and genetic synaptic zinc depletion mice was accompanied with reduced BDNF level." (PMID 23383172, 2013). "All these studies, together with our data, strongly suggested that high dose zinc supplementation-induced hippocampal zinc deficiency may impair the memory through BDNF deficit." (PMID 23383172, 2013). "Moreover, in another study on hypozincemia-induced cognitive dysfunction in rats, zinc deficiency led to the upregulation of DNMT1 transcription in their hippocampus and subsequent hypermethylation of the brain-derived neurotrophic factor (BDNF) gene and its downregulation." (PMID 33652690, 2021).
age (9 papers, 2009 to 2025). A temporal measurement of the time period elapsed since an identifiable point in the life cycle of an organism. "Age-related decline in short-term and spatial working memory is associated with decreased BDNF expression in hippocampus; conversely, increasing BDNF expression improves both short and long-term memory and contributes to neuronal survival and differentiation." (PMID 27768775, 2016).
Anorexia (9 papers, 2012 to 2023). Lack of desire to eat (loss of appetite). "That no phenotype related to feeding behaviour or anorexia was uncovered in this study does not imply that the effects of BDNF Val68Met will not be revealed in future studies, under the right conditions and with even more appropriate tools." (PMID 35625351, 2022).
atopic dermatitis (9 papers, 2013 to 2025). "To test the functional relevance of mMCP4 upregulation we next used NGF and BDNF neutralizing antibodies, as this treatment has been shown to successfully neutralize neurogenic inflammation effects in allergic dermatitis." (PMID 38891925, 2024). "Some studies reported the increased BDNF levels in patients with atopic dermatitis and androgenic alopecia." (PMID 35905107, 2022). "Several studies have confirmed increased levels of NGF or BDNF in atopic dermatitis, chronic spontaneous urticaria, symptomatic dermographism, acne vulgaris patients with depressive symptoms, and uremic patients with pruritus." (PMID 34620525, 2021). "Background/Objectives: This study aimed to investigate the relationship between serum brain-derived neurotrophic factor (BDNF) levels, disease severity, and various psychiatric symptoms in adolescents with atopic dermatitis (AD), compared to a healthy control group." (PMID 41153486, 2025). "Most recent studies have concentrated on the role of BDNF in pathogenesis of atopic dermatitis." (PMID 23108364, 2013).
bladder cancer (9 papers, 2011 to 2022). "For instance, the expression of miR-1-3p is markedly reduced in bladder cancer tissues; by targeting BDNF, miR-1-3p constrains the proliferation and invasion and expedites the apoptosis of bladder cancer cells." (PMID 34395415, 2021).
bladder pain syndrome (9 papers, 2011 to 2024). "As an important urinary neurotrophic factor, BDNF is detected to be abnormally elevated in some lower urinary tract diseases, such as overactive bladder, stress urinary incontinence, and interstitial cystitis." (PMID 31931832, 2020). "In what concerns clinical data, only one study has evaluated BDNF in the urine of bladder pain syndrome/interstitial cystitis patients." (PMID 22654715, 2011). "Moreover, in patients with bladder pain syndrome/interstitial cystitis, the urinary concentration of BDNF was high at baseline but was significantly reduced after botulinum toxin administration to the bladder trigone." (PMID 25951823, 2015). "Furthermore, urinary concentrations of BDNF are higher at baseline than after administration of botulinum toxin A to the bladder trigone in patients with bladder pain syndrome/interstitial cystitis." (PMID 24152577, 2013). "Previous studies have shown that dysregulation of brain-derived neurotrophic factor (BDNF) contributes to the development of stress urinary incontinence (SUI) and bladder pain syndrome/interstitial cystitis (BPS/IC)." (PMID 33859983, 2021). "Partly in agreement with these observations, another group observed a decrease in urinary NGF but not BDNF in patients with interstitial cystitis/bladder pain syndrome treated with hyaluronic acid." (PMID 38785946, 2024).
cognitive (9 papers, 2015 to 2025). "Increasing evidence indicates that hyperlipidemia and hypercholesteremia could lead to the down-regulation of BDNF and inhibition of hippocampal neurogenesis, which ultimately causes memory and cognition impairment." (PMID 40255947, 2024). "Interestingly, the BDNF Val66Met single nucleotide polymorphism (SNP), which reduces the activity-dependent release of BDNF and affects protein and mRNA levels, has been associated with an increased susceptibility to develop cognitive and psychiatric disorders." (PMID 30347685, 2018). "They reported activation of Nrf2 and BDNF/TrkB pathways as the main mechanisms of action, along with reductions in oxidative stress and pro-inflammatory cytokines—mechanisms implicated in GWI-related cognitive and emotional impairments." (PMID 40943436, 2025).
demyelination (9 papers, 2013 to 2025). "Therefore, LIPUS may cause an increase in the BDNF level and provide a neuroprotective effect and trophic support for reducing the entity of demyelination." (PMID 36077437, 2022). "For instance, stimulation of mGluR5 in astrocytes can lead to BDNF release, which supports myelin protein synthesis in the cuprizone-induced demyelination mouse model." (PMID 38146365, 2023). "Addition of FSD-C10 directly promoted remyelination in a chemical-induced demyelination model on organotypic slice culture, in a BDNF-dependent manner." (PMID 28112256, 2017). "Further, addition of FSD-C10 into LPC-induced demyelination cultures effectively promoted remyelination in a BDNF-dependent manner." (PMID 28112256, 2017). "In addition, administration of 7,8-DHF and TrkB agonist LM22A-4 promoted the repopulation of oligodendrocytes in the corpus callosum in a cuprizone demyelination model, while in vitro administration of BDNF in OPC cultures promoted OPC proliferation." (PMID 39428261, 2024). "In our current study, we have shown that TAK1 inhibitor OZ acts as an upstream regulator, transforming M1‐polarized microglia into M2 phenotype, rescuing the loss of oligodendrocytes, mediating inflammation, and increasing BDNF expression in CPZ‐induced demyelination mice model." (PMID 38648385, 2024). "The deletion of brain-derived neurotrophic factor (BDNF) in vivo, increased numbers of OPCs during cuprizone-induced demyelination and decreased levels of myelin proteins during remyelination, suggesting impairment in OPC differentiation." (PMID 23650566, 2013). "According to the findings of this study, it seems that vit B12 and EB have improved fear learning and memory, locomotor activity and increased phosphorylated Akt, BDNF and CREB proteins in rat hippocampus following EtB-induced demyelination in a dose dependent manner." (PMID 33953866, 2021).
developmental delay (9 papers, 2015 to 2024). "Meanwhile, antithyroid drug administration led to a reduction in serum BDNF levels and a developmental delay in primary hippocampal neurons in rats, and the addition of BDNF can rescue this variation." (PMID 38419953, 2024). "We extend the literature by including a group of children with non-ASD developmental delay and investigating the associations among diagnosis, BDNF concentrations, and common genetic variants of the BDNF gene while controlling for platelet count." (PMID 34518555, 2021). "T3 is one of the inducers of BDNF, and the absence of TH induces a developmental delay in primary hippocampal neurons through a decreased BDNF expression." (PMID 36473844, 2022). "Unadjusted mean BDNF concentration was higher in children with ASD than in children with typical development (standardized mean difference = 0.23; 95% CI 0.07, 0.38), but not children with non-ASD developmental delay." (PMID 34518555, 2021).
encephalitis (9 papers, 2013 to 2024). An acute inflammatory process affecting the brain parenchyma. "Such BDNF-loaded exosomes crosses BBB via intercellular adhesion molecule 1 (ICAM-1) which is upregulated under encephalitis-related inflammation." (PMID 38139999, 2023). "BDNF is described as elevated in other brain disorders, such as viral encephalitis and bacterial CNS infections." (PMID 35458486, 2022). "utilized naïve macrophage-derived exosomes for brain delivery of brain-derived neurotrophic factor (BDNF) for treating encephalitis." (PMID 34142628, 2021). "A neuroprotective and reparative role for microglial BDNF has indeed been postulated during the course of encephalitis, brain ischemia, and traumatic injury." (PMID 24089642, 2013). "In a mouse encephalitis model, exosomes derived from macrophages were found to efficiently deliver brain‐derived neurotrophic factor (BDNF) protein across the BBB, with a concentration increase of 2.2 and 3.6 times, compared to direct injection of BDNF protein and normal brain tissue, respectively." (PMID 38435823, 2024). "Microglial BDNF was first shown in microglia cultures and soon confirmed in different regions of the CNS during the course of various neurological disorders, such as viral encephalitis, traumatic injury, ischemia, multiple sclerosis, Parkinson's disease, neuropathic pain, and spasticity." (PMID 24089642, 2013). "HIV alters the processing of proBDNF, and in the CSF or brains of HIV infected people with HIV encephalitis, there was a decrease in BDNF and an increase in proBDNF." (PMID 28640909, 2017).
focal epilepsy (9 papers, 2012 to 2024). A seizure caused by a localized disorder. "Furthermore, the weighted median estimator specifically supported the hypothesis that plasma BDNF levels modestly reduced the risk of focal epilepsy (OR = 0.923; 95 % CI: 0.852–0.998, P = 0.046)." (PMID 38707431, 2024). "Meta-analysis shows that, usually, PWE had BDNF levels similar to general population, although patients with partial epilepsy showed lower BDNF levels." (PMID 36142325, 2022). "Differences in treatment regimens between patients with partial epilepsy and those with generalized epilepsy may be partly responsible for the lower BDNF levels in patients with partial epilepsy than in controls." (PMID 38707431, 2024). "BDNF is reduced in partial epilepsy but increased in generalized epilepsy." (PMID 38006577, 2024). "Our previous study showed that perturbed brain-derived neurotrophic factor and insulin-like growth factor 1 signaling in the central autonomic system contribute to autonomic dysfunction and impaired cerebral autoregulation in patients with focal epilepsy." (PMID 33920691, 2021). "Moreover, higher BDNF levels were associated with reduced odds of non-lesional focal epilepsy and focal epilepsy." (PMID 38707431, 2024). "In addition, BDNF serum level is reduced in patients with partial epilepsy." (PMID 38006577, 2024). "Particularly, in patients with focal epilepsy, CNTF levels were increased, while BDNF levels decreased both in the blood serum (BS) and LF, suggesting that high CNTF levels and low BDNF levels in the LF could be considered as non-invasive biomarkers of focal epilepsy." (PMID 38069144, 2023). "Levels of lacrimal and serum GDNF, serum BDNF, and cortisol were not significantly different between the groups of patients with focal epilepsy of different etiologies." (PMID 38069144, 2023).
Hepatic steatosis (9 papers, 2019 to 2025). Steatosis is a term used to denote lipid accumulation within hepatocytes. "While the findings of lower dysbiosis after vagotomy seem to be at odds with the higher brain inflammation and higher liver steatosis, most of these changes only occurred after CCl4 gavage and were associated with differential changes in BDNF expression." (PMID 34248683, 2021). "In the high-fat diet- (HFD) fed-mice, hepatic steatosis is induced by reducing the BDNF-TrkB expression." (PMID 34684653, 2021). "Further studies are needed to establish the beneficial effects of BDNF in the treatment of hepatic steatosis in other models of hepatic steatosis than db/db mice." (PMID 32175323, 2020). "As a result, hepatic steatosis was suppressed, suggesting that BDNF signaling in the CNS could contribute significantly to hepatic lipid metabolism." (PMID 38672461, 2024). "Taken together, reduced BDNF expression could induce hepatic steatosis via CNS appetite-regulating pathways and could contribute occurrence of hepatic inflammation by non-CNS pathways." (PMID 38672461, 2024). "Comparison of BDNF with thiazolidinediones in db/db mice revealed that BDNF was superior to thiazolidinediones in decreasing food intake, reducing body weight, and ameliorating hepatic steatosis and hepatomegaly." (PMID 32175323, 2020). "Increased expression of neurotrophic factors including GDNF, CNTF, BDNF, and NRG4 all alleviate hepatic steatosis." (PMID 32175323, 2020). "Thus, BDNF could potentially be used as an agent to treat hepatic steatosis." (PMID 32175323, 2020). "Among downregulated genes (KIT, NTRK2, MAMDC2, and ANXA13), KIT could regulate apoptosis, NTRK2 was revealed that capable of activating apoptosis pathways with Brain derived neurotrophic factor (BDNF), which may promote the progression of fatty liver disease." (PMID 38665091, 2024). "This suggests that BDNF does not regulate β-oxidation under a normal diet in mammals, but might diminish the effects of enhanced lipid oxidation, ultimately resulting in hepatic steatosis, under a high-fat diet challenge." (PMID 32612127, 2020).
hypercortisolemia (9 papers, 2016 to 2025). "Researchers suggest a possible relation between hypercortisolemia and lower BDNF levels, and recently, our laboratory reported, for the first time, a decrease in BDNF levels in the familial caregivers (32–84 years old) of AD patients." (PMID 27706235, 2016). "There is also evidence to suggest an interaction between hypercortisolism and brain-derived neurotrophic factor (BDNF), in that HPA-axis activation increases the glucocorticoid level, which in turn decreases BDNF expression in the hippocampus." (PMID 32477097, 2020).
hyperlipidemia (9 papers, 2017 to 2025). "Hyperlipidemia was found in 36.1% of the low BDNF group compared to 60.0% in the high BDNF group, corresponding to a statistically significant difference (p = 0.043)." (PMID 38397057, 2024). "Rhein is capable of treating cognitive dysfunction in high-fat diet-induced mouse models of hyperlipidemia by regulating the homeostasis of the microbiome, inhibiting the accumulation of macrophages, counteracting neuroinflammation, and promoting the expression of BDNF." (PMID 40529577, 2025).